ANLN (anillin, actin binding protein)
Diseases named in the same sentence as ANLN in open-access papers (continued):
Sharing a sentence is not in itself a finding about the gene and the disease.
breast carcinoma (continued). "Further prospective studies are needed to establish a potential role in the clinical management of breast cancer patients with tumors showing a high level of ANLN expression." (PMID 27863473, 2016). "Overall, our cohort data and the results from transcriptomics analyses support the finding that ANLN is a strong independent prognostic biomarker for breast cancer." (PMID 27863473, 2016). "Analysis of ANLN mRNA expression confirmed that high expression of ANLN was significantly correlated to poor overall survival in breast cancer patients." (PMID 27863473, 2016). "In conclusion, our data shows that ANLN expression is a strong prognostic factor in breast cancer and essential for cell cycle progression." (PMID 27863473, 2016). "Our study confirms the role of ANLN as a marker of poor prognosis, at the protein level, in an independent breast cancer cohort." (PMID 23547718, 2013). "In breast cancer, a transcriptomic study of DCIS to IDC breast cancer progression identified ANLN up-regulation in invasive tumour specimens relative to the pre-invasive phenotype." (PMID 23547718, 2013). "A 3-marker signature comprised of high PBK, high ANLN and low PDZK1 expression was associated with decreased recurrence-free survival (p < 0.001) and breast cancer-specific survival (BCSS) (p < 0.001)." (PMID 23547718, 2013). "Moreover, ANLN promoted doxorubicin resistance through direct interaction with RhoA in breast cancer cells." (PMID 41513610, 2026). "Moreover, miR-30a-3p acts as a promising suppressor gene by negatively regulating GAST expression and targets ANLN in breast cancer." (PMID 41361055, 2025). "ANLN has been suggested as a prognostic marker for breast cancer; however, its relevance in TNBC and its regulatory molecular mechanisms remain unknown." (PMID 39968094, 2025). "Moreover, miR-16-5p targets ANLN to accelerate the G2/M transition, shorten the overall cell-cycle duration, and promote apoptosis in breast cancer cells." (PMID 41573677, 2025). "Furthermore, breast cancer patients with elevated ANLN expression levels demonstrated a substantially worse overall survival rate." (PMID 39968094, 2025). "Moreover, previous studies have shown that a down-regulation of ANLN can enhance the sensitivity of pancreatic cancer cells to gemcitabine and inhibit doxorubicin resistance in human breast cancer cells." (PMID 40362181, 2025). "Furthermore, it was discovered that miR-16-5p suppressed ANLN expression contributing to the inhibition of breast cancer cells, similar to the overexpression of miR-16-5p." (PMID 37374977, 2023). "ANLN, an onco-gene to code actin-binding protein in tumorigenesis, has been found to up-regulate in rang of human cancers, such as lung adenocarcinoma, nasopharyngeal carcinoma, cervical cancer, breast cancer and colorectal cancer." (PMID 36482354, 2022). "Notably, in patients with breast cancer, low ANLN expression was correlated with better DMFS (P = 3.9e-07), RFS (P = 3.6e-10), and OS (P = 0.027), as demonstrated using Kaplan–Meier plotter." (PMID 35568883, 2022). "ANLN is highly expressed in diverse human tissues and cells, and it is considered an early predictor for cancer diagnosis, such as bladder urothelial carcinoma, colorectal cancer, pancreatic ductal adenocarcinoma, non-small cell lung cancer, and breast cancer." (PMID 35340220, 2022). "The key genes related to ANLN regulation also differ between different subtypes of breast cancer." (PMID 35578283, 2022). "ANLN is reported to boost breast cancer cell growth, migration, metastasis, and drug resistance." (PMID 36199577, 2022). "Recent findings have shown that the role of ANLN is significant in the immune reaction via association between ANLN and KDR, which may serve as a potential predictor of breast cancer survival." (PMID 35340220, 2022).
breast carcinoma (continued). "Previous studies in breast cancer cells have observed an increasing amount of cells stuck at the G2/M phase after ANLN knockdown, and this is consistent with the observed function in regulating cell cycle phases of ANLN in our work." (PMID 36199577, 2022). "Notably, ANLN is involved in the occurrence and progression of breast cancer and pancreatic cancer, and overexpression of ANLN mRNA and protein is associated with poor survival." (PMID 35568883, 2022). "All of these data suggested that miR-153-3p could attenuate lapatinib resistance by regulating ANLN in LR breast cancer cells." (PMID 34295807, 2021). "Also, we showed the exosomal circ-MMP11/miR-153-3p/ANLN axis in cell growth, metastasis, and chemotherapy resistance in LR-resistant breast cancer cells." (PMID 34295807, 2021). "In addition, immunohistochemistry on clinical breast cancer tissues also confirmed that ANLN was highly expressed in breast cancer." (PMID 34743685, 2021). "Recently, ANLN was shown to regulate breast cancer cell migration and stemness." (PMID 33854062, 2021). "Besides, our data also suggested that exo-circ-MMP11-secreted by LR breast cancer cells accelerated lapatinib resistance, proliferation, migration, invasion of breast cancer cells by regulating the miR-153-3p/ANLN axis." (PMID 34295807, 2021). "This study aimed to explore the role of miR-16-5p and ANLN in breast cancer (BC)." (PMID 34743685, 2021). "In summary, these results discovered that circ-MMP11 could be transferred by exosomes, and circ-MMP11 could elevate lapatinib resistance by regulating the miR-153-3p/ANLN axis in breast cancer cells." (PMID 34295807, 2021). "To date, ABPs that have been implicated in breast cancer cell migration, invasion, and growth include α-actinin 4 (ACTN4), actin filament-associated protein (AFAP-110), coronin-like actin-binding protein 1C (CORO1C), girdin, and anillin (ANLN)." (PMID 34194957, 2021). "All in all, miR-153-3p directly interacted with ANLN in LR breast cancer cells." (PMID 34295807, 2021). "Previous studies have shown that ANLN is highly expressed in multiple types of cancerous tumor, including bladder cancer, lung cancer, colorectal cancer, ovarian cancer, endometrial carcinoma, and breast cancer." (PMID 34743685, 2021). "ANLN promoted doxorubicin resistance in breast cancer cells by activating RhoA." (PMID 34344861, 2021). "Then, through bioinformatics tools, we speculated that miR-16-5p might directly target ANLN in breast cancer." (PMID 34743685, 2021). "Therefore, we further explored the relationship between miR-153-3p and ANLN in lapatinib resistance of LR breast cancer cells." (PMID 34295807, 2021). "In summary, our study found that the hub gene ANLN was upregulated in breast cancer and that miR-16-5p might target ANLN through comprehensive bioinformatics analysis." (PMID 34743685, 2021). "Therefore, miR-16-5p and ANLN will provide promising therapeutic targets for patients with breast carcinoma." (PMID 34743685, 2021). "However, in this case, it seems that ANLN is present in the nucleus, which controls the movement and invasion of breast cancer cells through JNK signaling." (PMID 32560530, 2020). "ANLN was considered as one of 17 markers for global genomic instability in breast cancer." (PMID 32560530, 2020). "Additionally, ANLN is involved in regulating the cell growth, migration, and metastasis of breast cancer." (PMID 32560530, 2020). "ANLN downregulation substantially suppressed the migration of breast cancer cells." (PMID 32560530, 2020). "For example, knocking down ANLN could strongly inhibit the migration ability of breast cancer cells." (PMID 32903581, 2020). "ANLN knockdown was demonstrated to inhibit cell growth and migration in breast cancer." (PMID 31392101, 2019). "ANLN was recently proposed as a prognostic biomarker independent of KI-67 (known proliferation marker) and being essential for cell cycle progression in primary breast cancers." (PMID 31636652, 2019).
breast carcinoma (continued). "All three primary cell surface receptors used for breast cancer subtyping (ER, PR, and HER2) were significantly associated with ANLN and KDR expression, suggesting that the synergistic effect of ANLN and KDR can affect cells’ transition from the triple negative to the luminal-like phenotype." (PMID 31636652, 2019). "Moreover, the functional role and a potential treatment predictive value of ANLN expression in patients with primary breast cancer were explored." (PMID 27863473, 2016). "We also show that depletion of ANLN induces cellular senescence in breast cancer cell lines." (PMID 27863473, 2016). "Immunohistochemical assessment of ANLN protein expression was performed in two well characterized breast cancer cohorts (n = 484) with long-term clinical follow-up data and the results were further validated at the mRNA level in a publicly available transcriptomics dataset." (PMID 27863473, 2016). "Nevertheless, breast cancer patients with a high tumor-specific ANLN expression may benefit from more aggressive treatment due to the apparent “poor prognosis” phenotype associated with high ANLN expression." (PMID 27863473, 2016). "Therapy targeting ANLN could provide a similar therapeutic effect as chemotherapy on breast cancer." (PMID 35991576, 2022). "Similarly, there are differences in the expression of ANLN in different subtypes of breast cancer." (PMID 35578283, 2022). "However, different immune-related patterns may indicate different mechanisms underlying the function of ANLN and UBE2T in different breast cancer subtypes." (PMID 35578283, 2022). "Additionally, to further validate the regulatory role of circ-MMP11 could be mediated by the miR-153-3p/ANLN axis in LR breast cancer cells, rescue assays were performed." (PMID 34295807, 2021). "Moreover, earlier kinds of literature have described that the ANLN expression could mediate drug-resistance of breast cancer cells to doxorubicin and anthracycline." (PMID 34295807, 2021). "Furthermore, these findings suggested that circ-MMP11 could be mediated transfer by exosomes, and circ-MMP11 could enhance the lapatinib resistance through regulating the miR-153-3p/Anillin (ANLN) in breast cancer." (PMID 34295807, 2021). "In addition, the overexpression of ANLN could abrogate the suppressive action of miR-153-3p on lapatinib resistance, cell growth, and metastasis of LR breast cancer cells." (PMID 34295807, 2021). "In addition, our results also confirmed that the regulatory role of exo-circ-MMP11 on lapatinib resistance, cell growth, and metastasis could be mediated by the miR-153-3p/ANLN axis in LR breast cancer cells." (PMID 34295807, 2021). "Silencing ANLN in non-small cell lung cancer (NSCLC) and breast cancer cell lines resulted in polynucleated cells and markedly inhibited cell proliferation." (PMID 41487287, 2025). "Studies have demonstrated that ANLN enhances the proliferation rate and colony formation of MDA-MB-231 breast cancer cells." (PMID 41573677, 2025). "KCNK1 expression was positively correlated with that of LDHA, Pan Kla, ZWINT, ECT2, ANLN, and EZR, reconfirming that KCNK1 played an important role in the proliferation and metastasis of breast cancer." (PMID 38905316, 2024). "ChIP-qPCR also showed that overexpression of LDHA blocked the inhibitory effect of KCNK1 knockdown on H3K18la and p300 binding of ZWINT, ECT2, ANLN, EZR, and LDHA in breast cancer cells." (PMID 38905316, 2024). "The results confirmed that the expression of ANLN and UBE2T was detectable in all types of breast cancer." (PMID 35578283, 2022). "The expression of ANLN and UBE2T in all types of breast cancer was confirmed by immunohistochemistry." (PMID 35578283, 2022). "This indicates that the expression of ANLN and UBE2T affects immune cells in different subtypes of breast cancer." (PMID 35578283, 2022).
breast carcinoma (continued). "Paraffin samples were used to examine the expression of ANLN and UBE2T in breast cancer tissues by immunohistochemistry, and three samples of each subtype of breast cancer were included." (PMID 35578283, 2022). "Another study also suggests a critical role in the immune response through a synergy between ANLN and KDR, which have prognostic value in breast cancer survival." (PMID 32560530, 2020). "However, as not all ER positive breast cancer patients respond to tamoxifen treatment and our finding of a strong correlation between ANLN expression and ER status, the possible association between ANLN expression and tamoxifen response was explored." (PMID 27863473, 2016). "In cohort II, Kaplan-Meier analysis and log-rank test revealed that breast cancer patients with high ANLN NF had a significantly shorter OS (p < 0.001), BCSS (p < 0.001) and RFS (p < 0.001) than patients with a low ANLN NF." (PMID 27863473, 2016). "TAGLN methylation states also relate to the prognosis of breast cancer, as TAGLN promoter methylation levels were negatively correlated with cellular proliferation and worse prognosis marker ANLN expression in our tumor-normal matched tissue panel." (PMID 26421063, 2015). "Specifically, over-expression of ANLN and KIF2C, and under-expression of MAPT strongly correlated with poor outcomes in breast cancer patients." (PMID 21679412, 2011). "The over-expression of ANLN and KIF2C, and the under-expression of MAPT consistently showed a strong correlation with poor survival in the breast cancer patients from both validation datasets." (PMID 21679412, 2011). "Among the downstream target genes regulated by KCNK1, ANLN and EZR are involved in cytoskeleton assembly, cell adhesion, and motility, so atomic force microscopy (AFM) was employed to assess the biophysical properties of breast cancer cells." (PMID 38905316, 2024). "Elucidating the role of ANLN and UBE2T in breast cancer is thus important." (PMID 35578283, 2022). "In addition, ANLN and UBE2T were highly expressed in breast cancer, especially in TNBC and HER2-positive breast cancers compared with luminal A and luminal B breast cancers." (PMID 35578283, 2022). "Breast cancer gene expression datasets were downloaded from the GEO database, and original data were analyzed in R. The TIMER database was used to analyze the relationship between ANLN and UBE2T and immune cell infiltration." (PMID 35578283, 2022). "ANLN and UBE2T are potential prognostic biomarkers and novel therapeutic targets in breast cancer." (PMID 35578283, 2022). "The expression of ANLN and UBE2T influence immune cells in different subtypes of breast cancer." (PMID 35578283, 2022). "ANLN and UBE2T are potential biomarkers for predicting the prognosis of breast cancer." (PMID 35578283, 2022). "UP-regulation of ANLN is observed in various human malignancies and exhibits a poor prognosis of cancers, such as in nasopharyngeal carcinoma (NPC), lung cancer, colorectal cancer (CRC), cervical cancer and breast cancer." (PMID 36482354, 2022). "In addition, the functional analysis suggested that the downregulation of ANLN partly reversed the suppressive role of exo-circ-MMP11 on cell growth and metastasis in breast cancer cells." (PMID 34295807, 2021). "Given that circ-MMP11 could be transferred by exosomes in breast cancer, and the effects of GW4869 on miR-153-3p and ANLN in this assay." (PMID 34295807, 2021). "Unlike FOXC1 and MET, the functional role of ANLN in breast cancer has not been studied extensively." (PMID 33854062, 2021). "The differential regulatory relationships between ANLN and KDR in different breast cancer cell lines and normal breast cells suggest a potential network rewiring between more and less malignant states in breast cancer cells, which warrants validation at the transcriptional level." (PMID 31636652, 2019).
breast carcinoma (continued). "Although experiments performed on only two different cell lines with differences in ER expression do not allow for general conclusions, we found that the impact of ANLN on these two breast cancer cells were similar, independent of ER status." (PMID 27863473, 2016). "Finally, three antibodies (PDZK1, ANLN, PBK) were successfully optimised on full-face paraffin embedded sections of breast cancer tissues and subsequently selected for screening on TMAs." (PMID 23547718, 2013). "However, the role of miRNAs targeting ANLN in breast cancer is still not clear, and further study on the specific mechanism of miRNAs and mRNA is indispensable for BC." (PMID 34743685, 2021). "It is noteworthy that even high grade breast cancer with severe nuclear atypia can be void of ANLN expression and that ANLN is a prognostic factor independent of proliferation (Ki-67 expression), suggesting possible additional roles for ANLN not directly linked to cytokinesis." (PMID 27863473, 2016). "ANLN expression in breast cancer cells plays an important role during cell division and a high fraction of nuclear ANLN expression in tumor cells is correlated to poor prognosis in breast cancer patients, independent of Ki-67, tumor size, hormone receptor status, HER2 status, nodal status and age." (PMID 27863473, 2016). "Analysis of the GSEA50567, GSEA65194, and GSEA43358 datasets showed that ANLN and UBE2T expression was higher in breast cancer than in normal tissues (P < 0.05) and higher in TNBC and HER2 overexpressing subtypes than in luminal A and luminal B subtypes (P < 0.05)." (PMID 35578283, 2022).